INS (insulin)
Diseases named in the same sentence as INS in open-access papers (continued):
Sharing a sentence is not in itself a finding about the gene and the disease.
Insulin resistance (continued). "Particularly, they had better glucose control inferred from significantly lower basal serum Glu and INS concentrations and lower level of HOMA-IR (60% difference), indicating lower insulin resistance." (PMID 36859449, 2023). "First, the blockade of IL-1 improves glycemia and β-cell secretory function; repression of the IL-6 receptor relieves diabetic renal injury and insulin resistance, and suppression of GATA-3 restores insulin sensitivity." (PMID 36776877, 2023). "Consistently, knockout of hepatic BACH1 in mice improved glucose tolerance and ameliorated insulin resistance compared with the control mice under HFD conditions, as indicated by the glucose tolerance test (GTT) and the insulin tolerance test (ITT)." (PMID 38129407, 2023). "Furthermore, functional studies suggest that hyperglycemia in Nidd5nsy congenic mice is due to both insulin resistance and a compensatory defect in insulin secretion in response to insulin resistance, suggesting that two or more genes may be involved rather than only one." (PMID 36693911, 2023). "By pathway analysis, we examined the indirect effects of FSH on BMD via the mediators Homeostatic Model Assessment for insulin resistance (HOMA-IR) and fasting insulin (FINS) after correction for confounding factors." (PMID 37670878, 2023). "Meanwhile, the secretion of hepatokine and metabolites related to lipid metabolism and insulin sensitivity is altered in NAFLD, which induces insulin resistance and MetS." (PMID 37941769, 2023). "Ectopic lipid deposition in the liver and skeletal muscle dampens peripheral insulin signaling and results in VAT inflammation, along with insulin resistance and subsequent T2D." (PMID 37176781, 2023). "The higher the insulin concentration needed to maintain low fasting glucose levels, the higher the HOMA-IR value, indicating the early development of insulin resistance." (PMID 38115031, 2023). "In this study, we demonstrated that RC significantly reduced insulin and glucose levels, thereby ameliorating HFD-induced insulin resistance." (PMID 36660274, 2023). "Insulin action occurs in a fiber-type specific manner, and fiber-type specific differences in GLUT4 accumulation affect the development of insulin resistance." (PMID 38203312, 2023). "In contrast, the concentrations of glucose, FRU, insulin, TG, MDA, TOS, and LPH, the insulin resistance index HOMA-IR, and the new-AIP index were significantly reduced." (PMID 38001776, 2023). "The HOMA model assessment in our present study further support that the liver glycogen content is a function of both insulin secretion (as in HOMA- β) and insulin resistance (as in HOMA-IR)." (PMID 37143025, 2023). "A study showed that palmitate-induced insulin resistance in C2C12 myotubes, when treated with Platycodon grandiflorum seeds enriched with luteolin, significantly activated insulin-independent AMPK and GLUT-4 translocation by 1.7-fold." (PMID 37298440, 2023). "Considering that insulin resistance is a major contributor to NAFLD, we examined glucose and insulin tolerance through GTT and ITT assays." (PMID 36864030, 2023). "Studies have shown that there are many methods currently used clinically to evaluate the islet β cell function and insulin resistance in patients with T2DM, including direct detection of insulin sensitivity and indirect detection of insulin sensitivity." (PMID 37893213, 2023). "These reductions in fasting insulin levels drove improvements in the homeostatic model assessment for insulin resistance (HOMA-IR), a surrogate marker for insulin resistance." (PMID 37797918, 2023). "Leptin and insulin signaling is inhibited by the SOCS3 gene product, which also participates in the response inhibition of various cytokine signals that result in insulin resistance." (PMID 36835260, 2023).
Insulin resistance (continued). "HOMA gives an estimate of basal insulin resistance (HOMA-IR, used to evaluate individual insulin resistance levels; HOMA-ISI, used to evaluate individual insulin sensitivity; HOMA- β, used to evaluate individual islets β indicators of cell function)." (PMID 37881496, 2023). "Considering that the previous findings strongly show that Mg2+ supplementation has the ability to improve insulin resistance, it seems that the improvement of muscle mass and function in T2DM is partly due to the improvement of the insulin signaling pathway." (PMID 37228689, 2023). "For example, maternal obesity results in male offspring hyperinsulinemia and insulin resistance by 3 months of age, accompanied by increased phospho-IRS1 S307 (decreased insulin signaling activity) and reduced phospho-Akt S473 in the offspring liver." (PMID 37855320, 2023). "Fasting insulin, the area under the curve (AUC) of insulin during OGTT, HOMA-IR, and the insulin resistance index were also significantly higher in the DM group than in the NC group." (PMID 36742405, 2023). "Homeostatic model assessment 2 of insulin resistance (HOMA2-IR) was calculated using values glucose and insulin levels using well established HOMA2 equation and calculator." (PMID 36918949, 2023). "To clarify how HCI induces insulin resistance by mechanisms other than intracellular lipids, we analyzed AKT phosphorylation, which occurs downstream of insulin signaling." (PMID 37389126, 2023). "Insulin resistance, the major pathological feature of MS and T2DM, is characterized by reduced sensitivity to insulin in various tissues such as the fat, liver, and muscle." (PMID 36042571, 2023). "Among the available methods of assessing insulin resistance, the homeostasis model assessment of insulin resistance (HOMA-IR) is the most frequently used, as it requires the determination of fasting glucose and insulin concentrations only." (PMID 37110142, 2023). "COMB therapy is also more favorable in the reduction of fasting insulin(FINS), total testosterone(TT), and homeostasis model assessment–insulin resistance(HOMA-IR) when compared to MET therapy." (PMID 37347114, 2023). "When insulin resistance is dominant, FINS shows a compensatory increase; insulin secretion decreases when the islet β-cell is damaged." (PMID 37849729, 2023). "The insulin resistance index HOMA-IR, calculated as (glucose [mg/dL] × insulin [μU/mL] ÷ 405), was lower by ~38% in the Gr-diet than the Cs-diet group (13.1 ± 1.9 vs. 21.1 ± 2.1, p < 0.05)." (PMID 38139180, 2023). "The reduction of insulin resistance has been proven to improve ovulation and fertility in women with PCOS, and this led to many studies regarding the possible role of insulin-sensitizing agents, particularly metformin, in the treatment of PCOS." (PMID 37409227, 2023). "The model describes the dynamic changes in glucose, insulin, free fatty acids (FFA), and inflammation levels in relation to weight gain and their roles in the progression of insulin resistance and T2D." (PMID 38026205, 2023). "Various reports describe improvements in insulin resistance (measured via HOMA-IR), fasting plasma insulin and fasting glucose following 25–60 min of walking or running at 50%–60% VO2 MAX (i.e., low to moderate intensity) three times per week." (PMID 37153211, 2023). "The DHS group had significantly higher values for TG (P < 0.001), TC (P < 0.05), fasting insulin (FINS, P < 0.05), fasting c-peptide (FCP, P < 0.05), and insulin resistance index (HOMA-IR, P < 0.05)." (PMID 37304842, 2023). "WD-fed mice had a higher likelihood of insulin resistance, as indicated by HOMA-IR scores considering fasting insulin levels." (PMID 37885804, 2023). "Four primary outcomes were identified: fasting blood glucose/fasting glucose, HbA1c, homeostatic model assessment for insulin resistance (HOMA-IR) and serum insulin/fasting insulin level." (PMID 35946077, 2023).
Insulin resistance (continued). "HOMA-IR and HOMA2-IR scores (used to assess insulin resistance) were higher in obese women compared to normal weight or overweight women in three studies; whereas the ISHOMA score, which assesses insulin sensitivity, was lower." (PMID 36520252, 2023). "The serum insulin level during GH therapy increased with the increasing duration of treatment and it was accompanied by insulin resistance, which was confirmed by a rise in the HOMA-IR and Insulin/Glucose ratio." (PMID 37497348, 2023). "We included two methods, the homeostatic model of insulin resistance (HOMA-IR) and the Gutt insulin sensitivity index (Gutt-ISI), to evaluate the fasting and post-glucose loading insulin sensitivities of these human subjects." (PMID 37188647, 2023). "Homeostasis model assessment of insulin resistance (HOMA-IR) is a simple and useful method for evaluating insulin sensitivity." (PMID 36983369, 2023). "The mechanism of BCAA overload causing insulin resistance may be the activation of the protein kinase mTOR (mammalian or mechanistic target of rapamycin), and the increase of acylcarnitine; mTOR is considered to be the main signal of crosstalk between BCAA and insulin." (PMID 36834946, 2023). "HOMA-IR was calculated from the fasting insulin and glucose values, and a HOMA − IR ≥ 2 was considered to indicate insulin resistance." (PMID 37274075, 2023). "An alteration in insulin signaling, predominantly in the IRS/phosphoinositide-3-kinase (PI-3K)/protein kinase B (PKB) axis, stimulates the development of insulin resistance." (PMID 38044940, 2023). "IFG has a higher hepatic insulin resistance and reduced early phase (first 30 min) insulin response to oral glucose, whereas IGT has a higher muscle insulin resistance and reduced early and late phase (60–120 min) insulin secretion." (PMID 37864066, 2023). "TMNB was also able to abrogate insulin resistance, measured by HOMA-IR, which showed that TMNB improved insulin sensitivity in diabetic rats, and this is in agreement with the reduction in serum insulin observed after treatment with TMNB." (PMID 36672202, 2023). "The glycemic control markers assessed included FPG, fasting insulin (FI), 2 h-OGTT, HbA1c, and homeostatic model assessment-insulin resistance (HOMA-IR)." (PMID 37679692, 2023). "Consistently, both the prophylactic and therapeutic use of TG dose-dependently decreased homeostasis model assessments of insulin resistance (HOMA-IR), an IR index which is negatively correlative with insulin sensitivity, compared with HFHSD control mice." (PMID 37056927, 2023). "There are studies suggesting the presence of tissue-specific insulin resistance in PCOS, in which metabolic tissues are resistant to insulin while the ovaries remain sensitive." (PMID 37371678, 2023). "In our study, both the olive oil diet and the fish oil diet improved insulin resistance, significantly improved FBG and FBI, and enhanced insulin sensitivity in obese mice induced by an HFD." (PMID 37513618, 2023). "However, the screening of new-onset diabetes after transplantation should consider the possible consequence of the induction of immunosuppressive therapy with a high dose of corticosteroids, which might promote glucose intolerance via increasing insulin resistance and reducing insulin sensitivity." (PMID 36769401, 2023). "The parameters with the greatest benefit from the low-GI and -GL interventions were glycated hemoglobin (HbA1c), homeostatic model assessment for insulin resistance (HOMA-IR) and fasting insulin." (PMID 38140319, 2023). "Although obesity is associated with increasing insulin resistance and pancreatic β-cell dysfunction, it remains unclear whether weight control during pregnancy, as recommended by the Institute of Medicine, would reduce the risk of GDM or the need for insulin therapy." (PMID 36793288, 2023). "Ultimately, we still have much to learn about how insulin signalling manipulates GLUT4 trafficking and how this becomes dysregulated in insulin resistance." (PMID 37248992, 2023).
Insulin resistance (continued). "Several genes are alternatively spliced in insulin resistance and T2DM; notably, the insulin receptor gene itself is alternatively spliced and regulated by its own hormone ligand, insulin." (PMID 37762628, 2023). "Therefore, we suggest that, besides TNF-α, there should be other factors in the group with obesity involved in insulin resistance, like high levels of leptin, along with low levels of adiponectin and IL-10, which may interfere with inflammation control and insulin sensitivity." (PMID 37215211, 2023). "The pathogenesis of insulin resistance is related to free fatty acid (FFA) accumulation, increased liver glucose production, and decreased glucose uptake in insulin-sensitive tissues." (PMID 36714242, 2023). "For example, genetic deletion of AKT has previously been shown to lead to severe insulin resistance and the development of type 2 diabetes, clearly demonstrating the importance of AKT for insulin and glucose response in vivo." (PMID 37126544, 2023). "In contrast, IKK-β activation in hepatocytes drives insulin resistance in the liver in response to ageing or a high fat diet, and myeloid-intrinsic IKK-β activation drives peripheral insulin resistance in muscle and fat tissue." (PMID 37311878, 2023). "Although the FFA are involved in metabolic changes and possibly in the progression of insulin resistance to the development of T2D, little is known about the relationship between OSA, adipose-tissue insulin sensitivity, and the FFA metabolism." (PMID 39434962, 2023). "Studies have shown that serine phosphorylation of IRS-1 (Ser636/639 and Ser307) results in an impaired insulin/PI3K/Akt signaling pathway and increased insulin resistance." (PMID 36982168, 2023). "Another mechanism leading to the development of insulin resistance by overexpression of the SOCS protein was through reduction in the tyrosine phosphorylation of IRS1 and IRS2 required for insulin transduction." (PMID 37529379, 2023). "Tracking the levels of immunoreactive insulin and HOMA-index, a significant reduction was also observed in group 1, which was using the selective serotonin receptor agonists and initially had insulin resistance." (PMID 37190510, 2023). "Insulin resistance is one of the hallmarks of metabolic diseases, thus we revealed the activity of liver-related PVN neurons in response to insulin." (PMID 37190103, 2023). "Fasting plasma glucose, triglycerides, as well as insulin and HOMA2-estimated insulin resistance were significantly higher in GDM, when compared to pregnant subjects with normoglycaemia." (PMID 37079606, 2023). "In this regard, insulin resistance is commonly found in patients with CKD55,56,57,58,59,60 in which the skeletal muscle represents the primary site of reduced insulin sensitivity." (PMID 36994079, 2023). "Homoeostasis model assessmentof insulin resistance (HOMA-IR) represents a surrogate measure of IR based onfasting glucose and insulin levels." (PMID 39076873, 2023). "Plasma levels of fasting glucose and insulin were evaluated, and the HOMA-IR was determined in order to assess glucose metabolism and insulin resistance in the offspring." (PMID 36969815, 2023). "Research has shown that insulin resistance is a critical link in the development of T2DM, as it reflects the body’s sensitivity to insulin and is a significant factor that influences the onset and progression of T2DM." (PMID 37065747, 2023). "This index has been shown to be a strong marker of insulin resistance, even better than the homeostatic model assessment of insulin resistance (HOMA-IR), quantitative insulin sensitivity check index, or fasting insulin plasma levels." (PMID 37391843, 2023). "Because the HFHSD markedly aggravated insulin resistance, we assessed OGTT and ITT in order to evaluate glucose tolerance and insulin sensitivity." (PMID 37047458, 2023). "Insulin and IGF-1 act on β cells to control their function and are determinant to compensate insulin resistance with an increased proliferation." (PMID 37371671, 2023).
Insulin resistance (continued). "This suggests that the absolute concentration of CoQ is crucial for insulin sensitivity, rather than the relative depletion compared to basal conditions, thus supporting the causal role of mitochondrial ceramide accumulation in reducing CoQ levels in insulin resistance." (PMID 38149844, 2023). "Based on these blood glucose and insulin concentrations we calculated the homeostasis model assessment for insulin resistance (HOMA-IR) and the Matsuda Index of insulin sensitivity." (PMID 37096321, 2023). "Here, we have shown a strong linear association not only of the FLI but also visceral and cardiac fat with increased fasting insulin resistance (HOMA-IR) and with reduced glucose clearance (OGIS) during OGTT, which is an index of insulin sensitivity." (PMID 37834099, 2023). "An indicator of insulin resistance, Homeostatic Model Assessment of Insulin Resistance (HOMA-IR), was determined based on the fasting glucose and fasting insulin levels." (PMID 37573386, 2023). "The decrease in the quantity and quality of skeletal muscle during the course of T2DM development significantly elevates insulin resistance of the whole body, resulting in an increased TDD requirement in T2DM patients receiving insulin treatment." (PMID 37489121, 2023). "First, obesity-driven insulin resistance in liver, white adipose tissue (WAT) and skeletal muscle, combined with insufficient secretion of insulin by pancreatic β-cells to overcome this resistance." (PMID 36836156, 2023). "There were positive relationships between fecal propionate levels and fasting serum insulin (FSI) (r = 0.245, p = 0.003), Homeostatic Model Assessment for Insulin Resistance (HOMA-IR) (r = 0.276, p = 0.001), and triglycerides (TG) (r = 0.254, p = 0.002)." (PMID 37432305, 2023). "Greater plasma insulin concentration and HOMA-IR and reduced QUICKI in the SC group compared with IC males (+100%, +290% and −9%, respectively) suggests insulin resistance." (PMID 37627441, 2023). "Increased activity of mTORC1 induces insulin resistance by phosphorylating insulin receptor substrate 1 (IRS-1), thus inhibiting insulin-stimulated glucose uptake." (PMID 38068805, 2023). "Higher 3′SL at all OGTT time points was associated with a generally more diabetogenic profile, with higher hepatic insulin resistance (HOMA-IR), lower insulin sensitivity (Matsuda index) and higher insulin secretion (C-peptide index 1)." (PMID 37764825, 2023). "Ethnic differences in fasting insulin and HOMA insulin resistance (higher among South Asian and black African Caribbeans) were reduced by >40% after adjustment for circulating 25(OH)D concentrations." (PMID 38123968, 2023). "This was accomplished using the added measures of HOMA-IR, which provides a representation of insulin resistance/sensitivity, while HOMA-B provides an index of insulin secretory function." (PMID 37421946, 2023). "Induction of insulin signaling with IGF-1 and reversal of insulin resistance suppresses α-synuclein aggregation and toxicity." (PMID 37746149, 2023). "The hyperinsulinemia-coupled insulin resistance phenotypes in BRSK2 variant carriers recalled the hotly debated viewpoint that β cells may initiate the development and progression of T2DM via crosstalk with insulin-sensitive tissues, such as the liver, adipose tissue, and skeletal muscle." (PMID 37188647, 2023). "The most commonly used method for evaluating insulin resistance is the homeostatic model assessment of insulin resistance (HOMA-IR), which is derived from the insulin and glucose in the fasting state." (PMID 36771345, 2023). "Related to insulin resistance, and also represented in the KEGG analyses on cecum, colon, and fecal pellets, were adipokine signaling (same fold-change direction) and insulin secretion (opposite direction)." (PMID 36922895, 2023).